PIRAT1 (PU.1 (SPI1) induced regulator of S100A8 and S100A9 alarmin transcription 1)
Synonyms: PIRAT; LINC00211; NCRNA00211
Gene: Long non-coding RNA gene on chromosome 2 (37,778,672 to 37,916,539, reverse strand). Ensembl gene ENSG00000237803.
Diseases named in the same sentence as PIRAT1 in open-access papers:
PIRAT1 is named in the same sentence as 3 diseases in open-access papers, as found by Europe PMC text mining. Sharing a sentence is not in itself a finding about the gene and the disease.
PIRAT1 shares sentences with these, for which no sentence is quoted: COVID-19 (3 papers); hematological malignancies (1); infection (1).